OR6Y1 (olfactory receptor family 6 subfamily Y member 1)
Description:
Odorant receptor.
Synonyms: OR6Y2; OR1-11
Tractability: Antibody: UniProt places it where antibodies can reach, with medium confidence; UniProt predicts a signal peptide or a membrane-spanning region; its Gene Ontology location is reachable by antibodies, with medium confidence.
Gene: Protein-coding gene on chromosome 1 (158,544,550 to 158,554,405, reverse strand). Ensembl gene ENSG00000197532.
Subcellular location: Cell membrane
Pathways (Reactome):
Sensory Perception: Expression and translocation of olfactory receptors
Gene Ontology:
Molecular function: olfactory receptor activity; G protein-coupled receptor activity
Biological process: detection of chemical stimulus involved in sensory perception of smell; G protein-coupled receptor signaling pathway
Cellular component: plasma membrane; membrane
Genetic constraint (gnomAD): Loss-of-function variants: 7 observed, 6.93 expected, observed/expected ratio (o/e) 1.01, 90% interval 0.57 to 1.76. That is too few expected variants to judge how well the gene tolerates losing a copy. Missense variants: 480 observed, 421.56 expected, observed/expected ratio (o/e) 1.14, 90% interval 1.06 to 1.23. Synonymous variants: 173 observed, 148.95 expected, observed/expected ratio (o/e) 1.16, 90% interval 1.02 to 1.32.
Homologues: Orthologues: chimpanzee OR6Y1 (97% identical), macaque OR6Y1 (96% identical), pig OR6Y1 (86% identical), dog OR6Y1 (86% identical), rabbit OR6Y1 (85% identical), rat Or6p1 (57% identical), mouse Or6p1 (56% identical). Paralogues in human: OR6A2 (55% identical), OR6B1 (52% identical), OR10A7 (47% identical), OR5V1 (47% identical), OR10A5 (45% identical), OR10A2 (43% identical), OR10A4 (43% identical), OR10C1 (43% identical), OR10G7 (43% identical), OR2D3 (42% identical), OR2D2 (42% identical), OR10G4 (42% identical), and 80 more.